MYC (MYC proto-oncogene, bHLH transcription factor)
Diseases named in the same sentence as MYC in open-access papers (continued):
Sharing a sentence is not in itself a finding about the gene and the disease.
breast cancer (continued). "To determine if the clinical impact of MYC DNA amplification or mRNA expression differs by breast cancer subtype, we analyzed the distribution of MYC DNA amplified and mRNA high expressing tumors in each breast cancer subtype." (PMID 31905596, 2019). "Endocrine resistant breast cancer cells are more dependent on MYC-regulated glutamine uptake compared with sensitive cells." (PMID 31428575, 2019). "To address the importance of high MYC expression for treatment efficacy, we employed two mouse models of breast cancer with low MYC expression; the MMTV-PyMT model with tumors syngrafted to FVB mice and an ER+ PDX model with tumors grafted to NSG mice." (PMID 30728358, 2019). "Consistently, MKC8866 strongly inhibited c-MYC-driven tumor growth in preclinical models of breast cancer in vivo." (PMID 30679434, 2019). "We investigated ATM, ATR and MYC at the transcriptional level [Molecular Taxonomy of Breast Cancer International Consortium cohort (n = 1950)] and at the protein level in the Nottingham series comprising 1650 breast tumours." (PMID 30746633, 2019). "We analysed genome-wide binding sites for three breast cancer-associated TFs (C/EBPβ, E2F1 and MYC) in MCF7 cells, and confirmed that a substantial fraction of these TFBSs resided in TEs." (PMID 31061680, 2019). "It was also demonstrated that the role of miR-29b in anti-angiogenesis and anti-tumorigenesis was through functional targeting of Akt3 protein and inducing VEGF and c-MYC arrest in breast cancer cells." (PMID 31590453, 2019). "By gene, the most frequent copy number event in claudin-low breast cancer was MYC amplification, found in 20% of cases." (PMID 31366361, 2019). "We show that ATM and ATR levels have clinicopathological, predictive and prognostic significance in MYC overexpressed breast cancer." (PMID 30746633, 2019). "This leads to a switch to lactate production, and the adjusted pH then directs USP28-mediated deubiquitination and stabilization of MYC, thereby promoting stem-like traits in breast cancer." (PMID 30688660, 2019). "Another study also shows that MYC inhibits TEAD transcriptional activity in MYC-driven breast cancer by suppressing the binding between TEAD and YAP/TAZ via AMPK-induced phosphorylation." (PMID 31212916, 2019). "We therefore provide a MYC-dependent model of breast cancer, which can be used to assay invivo tumour signalling pathways, proliferation and transformation from normal breast acini to invasive breast carcinoma." (PMID 31350286, 2019). "MYC is upregulated in the tamoxifen‐resistant breast cancer cell line MCF7/TAM, and these cells are more sensitive to tamoxifen after MYC knockout." (PMID 31573734, 2019). "The data further revealed that MYC transactivates the SLUG promoter to enhance breast cancer stem-like traits." (PMID 30688660, 2019). "It has been reported that the proportion of MYC DNA amplification as well as elevated mRNA expression is higher in triple-negative breast cancers (TNBCs) compared to other breast cancer subtypes." (PMID 31905596, 2019). "MYC overexpression is also documented in a number of solid tumors including lung, ovary and breast cancer." (PMID 30906568, 2019). "Previously, we have shown that the oncoprotein MYC is increased in estrogen independent and antiestrogen resistant breast cancer cells compared with parental MCF7 cells." (PMID 31428575, 2019). "In another study, MYC expression was up-regulated in aromatase inhibitor-resistant breast cancer cells and reduction of MYC expression significantly decreased cell proliferation in breast cancer cell lines." (PMID 30746633, 2019). "Resistance to a Class I PI3K inhibitor in a PI3K and MYC-driven model of metastatic breast cancer was associated with feedback activation of tyrosine kinase receptors, AKT, mTOR and MYC." (PMID 30906568, 2019). "Apart from these reports, TEAD and MYC also showed an anti-correlation in breast cancer patients that enabled the stratification of breast cancer subtypes." (PMID 31212916, 2019).
breast cancer (continued). "As expected, the expression of EPB41L4A-AS2 was negatively correlated with the expression of MKI67 and MYC both in breast cancer patients and the patients in the pancancer cohort." (PMID 30764831, 2019). "In breast cancers, MYC is increased in the estrogen, progesterone, and human epidermal growth factor receptor-2 (HER2) receptor triple-negative subtype of breast cancer, or TNBC." (PMID 31142021, 2019). "Second, breast cancer cells often overexpress MYC, which strongly enhances apoptosis through the TRAIL/DR5 pathway." (PMID 31839995, 2019). "One pathway implicated in PDGFRβ regulation is MYC, a transcriptional repressor of PDGFRβ, hence blocking ERK1/2-dependent MYC signaling induces expression and activation of PDGFRβ in breast cancer." (PMID 30777101, 2019). "In breast cancer and glioblastoma cell lines, the downregulation of MYC protein resulted in suppression of ABCC1, being a putative mechanism to sensitize tumors to chemotherapy." (PMID 31192117, 2019). "Of note, TPBCs showed significantly lower rates of ERBB2 and MYC amplification than ER-PR-HER2+ breast cancers (ERBB2: 53% vs. 85%, P = 0.001; MYC: 24% vs. 47%, P = 0.013)." (PMID 31410192, 2019). "We demonstrate the translational potential of an AMPK and BCL-2/BCL-XL co-targeting strategy in ex vivo and in vivo models of MYC-high breast cancer." (PMID 30728358, 2019). "c-MYC has been shown to play critical roles in multiple cellular pathways that promote breast cancer growth and progression." (PMID 30736840, 2019). "Reports have indicated that MYCBP plays a key role in cancer growth and progression via c-MYC regulation in breast cancer and other cancer types." (PMID 30736840, 2019). "We find, in a model of MYC-driven breast cancer, that pharmacological activation of AMPK strongly synergizes with BCL-2/BCL-XL inhibitors to activate apoptosis." (PMID 30728358, 2019). "More than half of the breast cancers with MYC-high status expressed a high level of BCL-2, BCL-XL, or MCL-1." (PMID 30728358, 2019). "Breast cancers with MYC and HER2 co-amplification are metastatic and exhibit a tumor initiating cell/cancer stem cell phenotype and poor prognosis." (PMID 31839995, 2019). "To examine the relevance of these findings in cancer, we investigated the status of AMPK activity and BIM in a set of clinical breast cancer samples with known MYC status." (PMID 30728358, 2019). "These MYC-driven tumours exhibit classic hallmarks of human breast cancer at both the pathological and molecular level." (PMID 31350286, 2019). "In this investigation, it is highlighted that SRSF1 in cooperation with MYC is involved in breast cancer progression." (PMID 32099613, 2019). "In our study, vitamin C suppressed stress-induced LDHA, thus altering the lactate production to inhibit the USP28/MYC/SLUG axis in breast cancer stem cells." (PMID 30688660, 2019). "Its localization is both cytoplasmic and nuclear in SiHa (cervical cancer cell line) while in 85% of SK-BR-3 breast cancer cells, a nuclear co-localization of MYC and PVT1 was observed." (PMID 30809433, 2019). "In summary, we report here the discovery and preclinical validation of a clinically applicable synthetic-lethal MYC-targeted therapeutic strategy for the treatment of breast cancer." (PMID 30728358, 2019). "MYC protein expression is also elevated via altered post-translational mechanisms and, altogether, about half of breast cancers display elevated MYC protein expression." (PMID 30728358, 2019). "It has gained much attention in recent years after it was demonstrated to contribute to ovarian and breast cancer pathogenesis independently from MYC." (PMID 31357500, 2019).
breast cancer (continued). "Consistent with our earlier findings suggesting dichotomous expression of MYC in primary breast cancer samples, five out of ten tumor samples were defined as MYC-high; whereas, the other half of the samples were MYC-low." (PMID 30728358, 2019). "Our study demonstrated that the non-canonical CACGCG E-box functions as a c-MYC binding site in HCC-B, and that c-MYC binds to the CACGCG motif in the NAMPT gene promoter in a breast cancer cell line." (PMID 31739577, 2019). "In conclusion, we provide strong clinical evidence that ATM signalling and ATR signalling can influence clinicopathological features and survival outcomes in patients with MYC overexpressed breast cancer." (PMID 30746633, 2019). "Out of 156 TNBC patients in TCGA breast cancer cohort, 57 (36.5%) tumors were found to be MYC DNA amplified and the same proportion of patients (36.5%) were classified as MYC mRNA high expressing tumors based on expression level." (PMID 31905596, 2019). "In breast cancers, MYC gene amplification (15%), MYC mRNA overexpression (22–35%) and MYC protein overexpression (40%) have been reported." (PMID 30746633, 2019). "Analysis of different data sets of breast cancer patients showed that MYC overexpression anti-correlated with ESR1 and GATA3 transcript levels." (PMID 29523784, 2018). "One of the interesting gene sets affected by somatic CNAs on chromosome 8 is ‘MYC-MAX complex’ which comprises oncogenes deregulated in 50% of human cancers including breast cancer." (PMID 30337938, 2018). "While in prostate cancer and breast cancer cells, the OGT/O-GlcNAcylation-mediated stabilization of c-MYC is tightly associated with the cell growth, suggesting the possibility of c-MYC as a potential upstream regulator of OGT target genes." (PMID 30082668, 2018). "In this regard, we have experimentally demonstrated that EPIC1, the top predictive lncRNA for iBET drug response, regulates iBET resistance in breast cancer by regulating MYC transcriptional activity." (PMID 30093685, 2018). "We confirmed that their transcriptional downregulation was not restricted to IMEC as the same pattern was induced by MYC overexpression in different luminal breast cancer cell lines." (PMID 29523784, 2018). "We sought to investigate if mRNA expression levels of candidate genes MYC and FAM84B are associated with clinical outcomes in human breast cancer." (PMID 30526553, 2018). "A similar increment in mammospheres formation was measured in luminal breast cancer cell lines upon MYC overexpression." (PMID 29523784, 2018). "To gauge the confounding nature of commonly amplified genes in breast cancer, we further performed multivariate analysis on the candidate genes with cases of amplification of MYC, FGFR1, CCND1, and ERBB2." (PMID 30181556, 2018). "In aromatase inhibitor-resistant breast cancer, overexpression of the oncogene MYC upregulates SLC1A5 expression via crosstalk between ER and HER-2." (PMID 29562706, 2018). "The MYC regulated super enhancer genes are the mammary neoplasms signature genes function in anchoring junction/adhesion, which is consistent with MYC’s function in regulation of cancer invasion." (PMID 29644114, 2018). "FAM84B is more commonly overexpressed than MYC in breast cancer, namely 9% of samples versus 4% of samples at 2 standard deviations (SD) above the mean for the METABRIC data and 23% versus 7% of samples for the TCGA data set." (PMID 30526553, 2018). "Chromosome conformation capture (3C)-based studies have identified higher-order chromatin structures connecting MYC and PVT1 to the breast cancer-associated 8q24 gene desert region." (PMID 30526553, 2018). "We demonstrated previously that deregulated MYC is also able to interfere with YAP/TEAD-dependent activity during breast cancer tumorigenesis." (PMID 30082728, 2018). "MYC amplification has been known as a frequent genetic alteration in breast cancer for several decades." (PMID 30526553, 2018).
breast cancer (continued). "Associations between Shannon indices for c-MYC CNV in pre- and post-neoadjuvant chemotherapy breast cancer samples and clinicopathologic features of tumors as well as patient survival were analyzed in 144 patients." (PMID 30420657, 2018). "Through the analysis of the TCGA data, it became clear that an increase in MYC activity and/or expression signature forms a subclass of TNBC (basal) breast cancer associated with poor outcome." (PMID 30526553, 2018). "First, we found that incubation of cells with different concentrations of EphrinA1 decreased the levels of EphA2, and CCND1 and c-MYC, consistent with previous reports showing an inverse correlation between EphA2 level and EphrinA1 in breast cancer cells." (PMID 30451837, 2018). "Specifically, miR-17 and miR-20a have been shown to be upregulated by 1.7–3.36 fold in estradiol-treated ER+ breast cancer cell lines via ERα-induced MYC/c-MYC upregulation." (PMID 30214383, 2018). "We demonstrate that HER2+ breast cancer tissues from AA women that demonstrate also have a high likelihood to show MYC amplification." (PMID 29523126, 2018). "We collected MYC‐driven spontaneous breast cancer tumors from MMTV‐MYC transgenic mice and established an allograft model by subcutaneously implanting tumor tissues into nude mice." (PMID 29769258, 2018). "Among the MYC targets, those that were specifically overrepresented within the basal-like breast cancers, which include modulators of kynurenine, prostaglandin, and Wnt pathways, are frequently deregulated in human cancers." (PMID 29523784, 2018). "VEGF-A is also found to stimulate the growth of breast cancer cells in a c-MYC dependent manner in xenograft models." (PMID 30239898, 2018). "In breast cancer, MEK inhibition resulted in acute ERK activity loss and subsequent c-MYC degradation that induced expression and activation of PDGFRB, DDR2 and VEGFR272, an RTK combination found in patients 6 (PT) and 10 (M) of our dataset." (PMID 29743718, 2018). "The genes located adjacent to the gene desert, MYC and PVT1 at one side and FAM84B at the other side, are candidates to play a role in 8q24 variant-mediated breast cancer susceptibility." (PMID 30526553, 2018). "In the TCGA data set, MYC is amplified in approximately 30% of basal-like breast cancers which suggest CDK inhibition as a plausible targeting strategy in MYC amplified basal-like breast cancer." (PMID 30558195, 2018). "These clinical observations suggest that high expression of CLK2 and MYC amplification worsen the prognosis of particular subtypes of breast cancer patients and that CLK inhibitor would be more effective to these poor prognosis cancers." (PMID 29769258, 2018). "Genetic substitution of CDK1 gene has been shown to cause embryonic lethality, and its inhibition has been suggested as a potential therapy for MYC-dependent breast cancer." (PMID 30514202, 2018). "For paclitaxel we found that three genes were reported to be associated with ovarian cancer (HOXB2, MYC, and TFPI2; p=0.024) and two genes were strongly associated with tumorigenesis of breast cancer (DUSP2 and ITGA3; p<0.001)." (PMID 29416679, 2018). "Studies involving MYC overexpression and knockdown in human mammary epithelial and breast cancer cells further corroborated this relationship." (PMID 29506475, 2018). "The responsible phosphorylation sites in c-MYC have been elucidated through mutagenesis in fibroblasts and detected as phosphorylated in mammary tumors." (PMID 30001368, 2018). "Several previous studies reported MYC regulation by metformin, via either microRNA regulation in breast cancer or protein degradation in prostate cancer." (PMID 30221473, 2018). "The average expression of MYC-induced oncogenes is strongly upregulated in basal-like breast cancers and predictive of a worst prognosis for this specific molecular subtype." (PMID 29523784, 2018).
breast cancer (continued). "We show here that, while the 8q24 amplicon is frequently observed in all breast cancers, an increased MYC transcript level is relatively uncommon and mostly occurring in the TNBC (basal) subtype." (PMID 30526553, 2018). "They report that a novel, orally administered CLK2 inhibitor (T‐025) induces exon skipping, which results in cancer cell growth reduction, especially in breast cancer (BCa) MYC‐driven tumors." (PMID 29789342, 2018). "So we can’t prove that RBMS2 functions through c-MYC in breast cancer and more experiments are needed to prove it." (PMID 30514345, 2018). "In the MYC-dependent breast cancer, another alternative is to target MYC’s SL partner gene CDK1, as reported in some small interfering RNA (siRNA) experiment." (PMID 29855504, 2018). "This study supports the notion that MYC-driven tumor initiation relies on cell reprogramming, which is mediated by the activation of MYC-dependent oncogenic enhancers, thus establishing a therapeutic rational for treating basal-like breast cancers." (PMID 29523784, 2018). "E2F7 is a known cell cycle regulator that is associated with poor survival in squamous cancers, upregulates c-MYC in various cancer cell lines, and induces tamoxifen resistance in breast cancer." (PMID 30092011, 2018). "The RNA‐sequencing data of TCGA showed DNMT3A and MYC were highly expressed in TNBC tissues compared with in other breast cancer subtypes." (PMID 30324719, 2018). "These tumors tend to overexpress glutaminase, suggesting a functional relationship between MYC activation and glutamine dependence in breast cancer." (PMID 29740540, 2018). "TRPS1 is co-amplified with MYC in breast carcinomas with an increased proliferation rate, and silencing TRPS1 reduces proliferation of BT474 cells." (PMID 30071870, 2018). "For example, it has been reported that despite dramatic regression of c-MYC inducible mouse mammary carcinoma after doxycycline withdrawal, there remains residual tumour cells that generate tumour recurrence independent of increased c-MYC expression." (PMID 30451834, 2018). "Prior studies have shown that CDK9 mediated transcription regulation of MYC is important in therapy resistance in breast cancer and disease maintenance in hepatocellular carcinoma." (PMID 28404924, 2017). "Our recent work demonstrated that the signalling adaptor p62 enhances breast cancer stem-like properties through downregulating let7a/b expression to stabilize MYC mRNA." (PMID 28968743, 2017). "So, in vitro functional studies are needed to explore the role of PCAT-1 in regulation of MYC expression in breast cancer tissues." (PMID 28989584, 2017). "We demonstrated that TIM increased the invasive and migratory abilities of breast cancer cells at least partially through regulation of MYC expression." (PMID 28464854, 2017). "Consistently, we found that MYC expression is inversely correlated with PRODH expression in primary breast cancer tissue compared to metastases tissue of patients." (PMID 28492237, 2017). "In summary, we demonstrate that the signaling adaptor p62-promoted breast cancer stem-like properties through stabilizing MYC mRNA at the post-transcriptional level." (PMID 27345399, 2017). "MYC is a famous oncogene, its knockdown significantly inhibited mammosphere formation and breast cancer cell invasion." (PMID 28490334, 2017). "In breast cancers, DOT1L is associated with poorer survival and aggressiveness, and DOT1L can cooperate with c-MYC and histone acetyltransferases to activate EMT and enhance cancer stem cell-like properties." (PMID 28804523, 2017). "Taken together, these results indicated that MYC is necessary for the p62-promoted stem-like properties in breast cancer." (PMID 27345399, 2017). "In further support of our findings, two previous studies propose a possible stimulation of cell proliferation and a parallel inhibition of cell motility and invasiveness by MYC in breast cancer cells." (PMID 28423716, 2017).